CRP (C-reactive protein)
Diseases named in the same sentence as CRP in open-access papers (continued):
Sharing a sentence is not in itself a finding about the gene and the disease.
Thrombocytopenia (continued). "The results showed that gestational age, birth weight, intrauterine infection, patent ductus arteriosus, white blood cell count, thrombocytopenia, and CRP level were not statistically different between the two groups (P > 0.05)." (PMID 35633977, 2022). "This meta-analysis study consists of pregnant and non-pregnant groups, and thrombocytopenia and CRP levels were found to be lower in pregnant women compared to non-pregnant women." (PMID 36263236, 2022). "Our study reveals a higher prevalence of complicated appendicitis and comorbidities in older patients and suggests that a lack of epigastric pain, thrombocytopenia, and higher serum CRP level (>5 mg/dl) are characteristics of older patients." (PMID 35004106, 2022). "Our study reveals a higher prevalence of CA and comorbidities in older patients, and suggests that a lack of epigastric pain, thrombocytopenia, and higher serum CRP level are characteristics of older AA patients." (PMID 35004106, 2022). "ATBF cases were distinctly different and patients showed much milder systemic reactions: no hepatocellular injury, jaundice, rhabdomyolysis, or thrombocytopenia; and significantly lower C-reactive protein levels (mean 35 mg/L; p = 0.034)." (PMID 34286684, 2021). "Nonspecific multisystem symptoms in patients with thrombocytopenia and increased CRP, hyponatremia, transaminitis with involvement of lungs, kidneys and brain in a febrile child should strike the diagnosis." (PMID 34508431, 2021). "Furthermore, the binding of C-reactive protein (CRP), an acute phase protein upregulated in acute infections and inflammation, to platelets drives another pathway leading to thrombocytopenia in ITP." (PMID 34831457, 2021). "Future research to clarify the predictive value of CRP, WBC, and thrombocytopenia is warranted." (PMID 33340348, 2020). "The remaining patient recovered without treatment and showed elevated CRP values, leukocytopenia, and thrombocytopenia." (PMID 32102367, 2020). "CRP, WBC, and thrombocytopenia may be useful tools in predicting patients who will develop organ dysfunction and is a vital area of future research." (PMID 33340348, 2020). "It is worth noting that non-survivors showed lower blood pressure, higher level of CRP (C reactive protein), and progressive thrombocytopenia, cardiac injury, liver injury and kidney injury from about the 3rd day post intubation." (PMID 33117833, 2020). "Patients with severe systemic inflammation had higher CRP levels and they were more likely to exhibit leukopenia, thrombocytopenia and DIC, than patients without systemic inflammation." (PMID 31384283, 2019). "For CoNS infection episodes (n = 35), BDL showed a positive correlation with CRP (rs = 0.48; p = 0.004), but not with I/T ratio, total leukocyte count, or thrombocytopenia." (PMID 29679983, 2018). "In contrast, those patients who were subsequently found to be DENV seronegative did not tend to present with leukopenia or thrombocytopenia, and had higher neutrophil and CRP values." (PMID 30274405, 2018). "The patients showed characteristic clinical symptoms (sudden onset of flu-like symptoms), impairment of laboratory parameters (thrombocytopenia, rise in levels of serum creatinine, leukocytes, LDH, CRP, and low levels of serum albumin), proteinuria, and hematuria." (PMID 30541481, 2018). "The presence of rash (36%) and laboratory findings of neutropenia, leukopenia, thrombocytopenia, but not elevated C-reactive protein, were distinct from findings in DENV-seronegative patients." (PMID 30274405, 2018). "In our study, laboratory data, which could not be retrieved in detail for all patients, often showed elevated levels of C-reactive protein, LDH, and liver enzymes, paralleled by thrombocytopenia." (PMID 29912688, 2018).
Thrombocytopenia (continued). "The present study showed that NEC cases with bowel perforation were more likely to exhibit an abnormal WBC count, thrombocytopenia, significant increase of CRP, and relatively low blood pH compared to those without bowel perforation." (PMID 27375739, 2016). "The laboratory alterations included C-reactive protein levels of 48 mg/dL (reference value of 0.1 mg/dL), marked cell atypia, serum glutamic oxaloacetic transaminase (GOT) levels of 78 URF/mL (reference value of 4–36 URF/mL), and thrombocytopenia." (PMID 27581616, 2016). "On presentation, her blood results showed a marked increase in C-reactive protein (CRP = 260.9 mg/L), a decline in renal function (estimated glomerular filtration rate (eGFR) = 38 mL/min/1.73m2, urea = 11.7 mmol/L, and creatinine = 124), and microcytic hypochromic anemia with thrombocytopenia." (PMID 40162125, 2025). "Key clinical features, including cat exposure, thrombocytopenia, and a slight elevation of serum C-reactive protein, may aid early diagnosis even in the absence of tick bite history." (PMID 41143065, 2025). "Laboratory findings may be normal, as well as decreased leukocyte count, decreased lymphocyte count, thrombocytopenia, increased transaminases, increased lactate dehydrogenase (LDH), creatine kinase-myoglobin elevation C Reactive Protein (CRP) and Total bilirubin and the decrease in albumin." (PMID 39139154, 2024). "This cluster was characterized by a less severe MIS-C phenotype with a lower prevalence of hypotension/shock, lower CRP, ferritin, NT-proBNP, and D-dimer levels, less hyponatremia and thrombocytopenia, no ventricular dysfunction, and few chest X-ray abnormalities compared to the other clusters." (PMID 37046304, 2023). "In 2 patients (No 2 and 8), the White blood cell count and the neutrophil ratio increased; leukocytopenia was noted in 5 patients (No 1, 3, 4, 5, and 6); 2 patients (No 3 and 7) developed thrombocytopenia; all the patients had increases in C reactive protein and procalcitonin to different extents." (PMID 37443518, 2023). "When leukocyte and thrombocyte numbers do not diminish further or when CRP and LDH do not increase any more, the pyrexia score quickly falls although the associated symptoms of pyrexia, such as fever, leukopenia or thrombocytopenia, might still be severe." (PMID 36006943, 2022). "Lymphocytopenia and thrombocytopenia suggestive of bone marrow suppression are common in the acute phase of MIS-C, as opposed to Kawasaki disease, where thrombocytosis is more common than thrombocytopenia and CRP may not be as elevated." (PMID 35433557, 2022). "In addition, the perforated NEC group had higher prevalence of abnormal WBC count, thrombocytopenia, elevated CRP, and blood glucose levels than nonperforated NEC group." (PMID 27375739, 2016). "However, we found that the positive predictive value (PPV) for combination of leukopenia, thrombocytopenia, elevated aminotransferase and low CRP is 89.5% and negative predictive value (NPV) is 37.4%." (PMID 24138072, 2013). "Similarly, there was a positive correlation with inflammatory markers, CRP and IL-6, and creatinine and a negative correlation with platelet count, indicative of a rising inflammation, a worsening kidney function, and thrombocytopenia, potentially attributable to worsening HIV and general condition." (PMID 39998057, 2025). "Control infants with thrombocytopenia and with high CRP had the highest rate of severe ROP, 100% (8/8), while AA/DHA supplemented infants without thrombocytopenia and without high CRP had the lowest rate, 15.9% (10/63)." (PMID 39702768, 2025). "Laboratory test results for 19 neonates showed only a few with increased leukocyte count and C-reactive protein (CRP), and no cases of lymphocytopenia or thrombocytopenia." (PMID 38738039, 2024).
Thrombocytopenia (continued). "Although the basic popular markers of innate immunity (NLR, thrombocytopenia, and CD64) can be equally applied in early neonatal sepsis of various etiologies with satisfactory operational characteristics, CRP is largely stimulated by Gram-negative pathogens." (PMID 34840718, 2021). "A chest X-ray was negative and blood examinations showed increase C-reactive protein (201 mg/L) mild anaemia (Hb 12.2 g/dL, Ht 35%), leukopaenia (WBC 3200/μL) and thrombocytopaenia (45,000/μL)." (PMID 31088460, 2019). "The positive predictive value (PPV) for combination of leukopenia, thrombocytopenia (< 150 × 103/cmm), elevated aminotransferase (AST/ALT > 1.5) and low CRP (< 20 mg/L) is 89.5%, while the negative predictive value is 37.4%." (PMID 24138072, 2013). "Laboratory data revealed severe leukopenia (90/μL; Laboratory Risk Indicator for Necrotizing Fasciitis [LRINEC] score = 2), thrombocytopenia (1 × 104/μL; thrombocytopenia is not counted in the LRINEC score), and elevated C-reactive protein levels (31.01 mg/dL; LRINEC score = 4)." (PMID 39058861, 2024). "However, atypical features emerged with non-hemolytic anemia, positive direct Coombs test, thrombocytopenia, hypergammaglobulinemia, and high ESR:CRP ratio." (PMID 36251071, 2023). "When the MPV and CRP values of the patient and control groups were compared, 5 (3.7%) of the patients were not included in the comparison since the MPV could not be read due to significant thrombocytopenia." (PMID 41578803, 2025).
endothelial dysfunction (618 papers, 2004 to 2026). In vascular diseases, endothelial dysfunction is a systemic pathological state of the endothelium (the inner lining of blood vessels) and can be broadly defined as an imbalance between vasodilating and vasoconstricting substances produced by (or acting on) the endothelium. "From a pathophysiologic perspective, CRP elevation reflects underlying myocyte injury, IL-6–mediated hepatic acute-phase response, endothelial dysfunction, and fibrotic remodeling." (PMID 41596517, 2026). "This progression is closely associated with systemic inflammatory markers, including CRP and IL-6, which exacerbate endothelial dysfunction and plaque instability in NCVs." (PMID 41517773, 2026). "A cross-sectional study also reported elevated CRP levels in patients with periodontitis and examined endothelial dysfunction caused by the persistent pro-inflammatory status associated with periodontitis." (PMID 40572711, 2025). "CRP is also associated with endothelial dysfunction, as reported to forecast cardiovascular-related disorders." (PMID 39858439, 2025). "Migraine with aura has been repeatedly associated with endothelial dysfunction and increased risk of vascular events, both of which are linked to elevated circulating CRP levels." (PMID 41402545, 2025). "The CRP/Alb ratio has been associated with inflammation and endothelial dysfunction, particularly in resistant hypertension." (PMID 41302334, 2025). "Elevated levels of inflammatory cytokines such as IL-6, TNF-α, and CRP have been associated with cartilage degradation, endothelial dysfunction, and metabolic dysregulation." (PMID 40843198, 2025). "Selected biomarkers were chosen based on prior evidence linking them to platelet activation (sCD40-L), systemic inflammation (hs-CRP), and endothelial dysfunction (VCAM-1) – all of which are implicated in CMVO pathogenesis." (PMID 40988197, 2025). "CRP is strongly associated with endothelial dysfunction (ED) in hyperlipidemic individuals, reinforcing the tight interplay among inflammation, lipids, and endothelial damage." (PMID 41169425, 2025). "Consistent with these interventional findings, periodontitis is also associated with endothelial dysfunction and vascular inflammation, accompanied by elevated neutrophil counts and circulating IL-6 and C-reactive protein (CRP)." (PMID 41515997, 2025). "Elevated CRP reflects the intensity of the inflammatory response and is linked to cytokine release, endothelial dysfunction, and blood–brain barrier permeability, facilitating neuroinflammation and neuronal dysregulation." (PMID 41303282, 2025). "Chronic dental infections, including untreated dental caries, have been linked to the release of inflammatory mediators such as CRP, which can cause endothelial dysfunction and vascular changes." (PMID 40013198, 2025). "The high level of CRP was linked to an increased risk for rupture of plaque and vascular thrombosis since CRP mediates endothelial dysfunction and destabilises atherosclerotic plaques toward rupture." (PMID 41296388, 2025). "CRP, another key predictor in our model, serves as a surrogate marker for systemic inflammation and has been associated with endothelial dysfunction and thrombogenesis." (PMID 40804452, 2025). "Third, C‐reactive protein (CRP), a biomarker commonly associated with vascular inflammation and endothelial dysfunction, showed positive correlations with succinate and oxoglutarate and negative correlations with GGR." (PMID 40577101, 2025). "The onset and worsening of endothelial dysfunction are associated with increased levels of inflammatory markers and mediators, including CRP, intercellular and vascular cell adhesion molecules, fibrinogen, interleukin (IL) 1b, and IL-6." (PMID 38965367, 2025). "Elevations inhs-CRP are associated with endothelial dysfunction, resulting in vascular injury,reduced blood flow to the kidneys, and reduced renal function." (PMID 39355575, 2024).
endothelial dysfunction (continued). "Elevated CRP is also associated with endothelial dysfunction, which can impair the cerebral blood flow and oxygen delivery to the brain." (PMID 39596303, 2024). "It represents a proinflammatory and microvascular disease associated with higher circulating levels of C-reactive protein levels, endothelial dysfunction, genetic mutations of cholesterol metabolism, and subclinical vascular disease." (PMID 39035774, 2024). "CRP, a key acute-phase protein associated with inflammatory and infectious processes, as well as tissue injury, serves as a reliable indicator of endothelial dysfunction in CAD." (PMID 39202269, 2024). "C-reactive protein (CRP) and its monomeric form (mCRP) are associated with endothelial dysfunction and amyloid plaque instability, contributing to neuroinflammation and neurodegeneration." (PMID 39347146, 2024). "Concurrently, systemic inflammation, evidenced by NLRP3 overexpression and elevated levels of IL-6, sCD40-L, and C-reactive protein, was associated with endothelial dysfunction biomarkers and increased in post-COVID patients with impaired gas exchange." (PMID 38867241, 2024). "IL‐6 also increases the risk of CVD through endothelial dysfunction by inducing CRP synthesis in the liver, which provokes leukocytes recruitment and perpetuates inflammatory responses." (PMID 39160453, 2024). "In the context of increased intestinal permeability, TMAO is also linked to C-reactive protein (CRP), endothelial dysfunction, and elevated blood levels of the LPS endotoxin." (PMID 38646625, 2024). "CRP from liver synthesis plays an important role in the inflammatory processes associated with MetS, insulin sensitivity, endothelial dysfunction, and fibrinolysis failure." (PMID 38140392, 2023). "Conversely, a study of obese Mexican children and adolescents showed that changes in the gut microbiota were associated with increased levels of CRP, decreased adiponectin levels, and increased endothelial dysfunction markers." (PMID 37755767, 2023). "In a subset of the Nurses’ Health Study, the MD was linked to reduced inflammation markers (IL-6 and C-reactive protein) and endothelial dysfunction, even after adjusting for traditional CVD risk factors." (PMID 38042258, 2023). "Elevated hs-CRP levels have been associated with increased cardiovascular risk and endothelial dysfunction." (PMID 37700972, 2023). "Women with PCOS and hyperinsulinemia have low-grade chronic inflammation which reflects the CRP levels and possibly causes endothelial dysfunction." (PMID 38027110, 2023). "Endothelial dysfunction and C-reactive protein (CRP) are also linked to TMAO and associated with elevated LPS toxin." (PMID 36076760, 2022). "It has been suggested that CRP is associated with anthropometric measures of inflammation, while suPAR is linked to cellular and vascular inflammatory processes, such as endothelial dysfunction and atherosclerosis." (PMID 35102231, 2022). "The serum biomarker with the most promising results seems to be the high sensitivity C Reactive Protein (hsCRP), being probably representative of the underlying status of chronic inflammation characterizing endothelial dysfunction and thus both ED and CVDs." (PMID 36009395, 2022). "SCH is associated with endothelial dysfunction, coagulation abnormalities, and increased levels of C-reactive protein, which increases the risk of cardiovascular diseases, similar to overt hypothyroidism and systemic inflammation as in low T3 syndrome." (PMID 36078968, 2022). "The increased level of CRP has been associated with inflammation and endothelial dysfunction, which ultimately promotes an increase in cardiac mass." (PMID 35535358, 2022). "Chronic inflammation plays a major role in coronary microvascular impairment, high levels of C-reactive protein (CRP) being associated with endothelial dysfunction." (PMID 35950156, 2022).